FAM110B (family with sequence similarity 110 member B)
Description:
May be involved in tumor progression.
Synonyms: C8orf72; MGC39325
Tractability: PROTAC: its protein half-life has been measured.
Gene: Protein-coding gene on chromosome 8 (57,993,956 to 58,204,279, forward strand). Ensembl gene ENSG00000169122.
Subcellular location: Cytoplasm; Cytoplasm, cytoskeleton, microtubule organizing center, centrosome
Subcellular location (Human Protein Atlas): Cytosol; Mitochondria
Gene Ontology:
Molecular function: protein binding
Cellular component: cytosol; mitochondrion; centrosome; cytoplasm
Genetic constraint (gnomAD): Loss-of-function variants: 6 observed, 20.94 expected, observed/expected ratio (o/e) 0.29, 90% interval 0.16 to 0.57. The upper end of that interval is the gene's LOEUF score, 0.57, which puts it in group 2 of 6, group 1 being the genes least tolerant of losing a copy. Missense variants: 434 observed, 522.49 expected, observed/expected ratio (o/e) 0.83, 90% interval 0.77 to 0.9. Synonymous variants: 226 observed, 226.45 expected, observed/expected ratio (o/e) 1, 90% interval 0.89 to 1.11.
Homologues: Orthologues: chimpanzee FAM110B (99% identical), macaque FAM110B (99% identical), mouse Fam110b (95% identical), rabbit FAM110B (95% identical), rat Fam110b (95% identical), guinea pig FAM110B (94% identical), dog FAM110B (91% identical), pig FAM110B (88% identical), tropical clawed frog fam110b (86% identical), zebrafish fam110b (69% identical). Paralogues in human: FAM110A (35% identical), FAM110C (22% identical), FAM110D (18% identical).
Diseases named in the same sentence as FAM110B in open-access papers:
FAM110B is named in the same sentence as 22 diseases in open-access papers, as found by Europe PMC text mining. Sharing a sentence is not in itself a finding about the gene and the disease. The quoted sentences say what the papers report.
prostate carcinoma (4 papers, 2020 to 2024). A carcinoma that arises from epithelial cells of the prostate gland. "Previous studies have shown that FAM110B is also involved in the regulation of antigen presentation on the surface of prostate cancer cells, thus allowing the immune escape of tumor cells." (PMID 39170745, 2024). "In prostate cancer cells, FAM110B knockdown reduces cell viability and induces apoptosis, suggesting its potential as a therapeutic target." (PMID 37275958, 2023). "FAM110B has been proved to have an essential role in multiple cancer hallmarks and progression of many types of cancer such as prostate cancer." (PMID 32859214, 2020). "Notably, the therapeutic potential of targeting FAM110B has been demonstrated not only in pancreatic and colon cancers, but also in several other cancer types, including non-small cell lung cancer and prostate cancer." (PMID 37275958, 2023).
breast carcinoma (3 papers, 2018 to 2024). "It is stated that FAM110B is a survival predictor of breast cancer stem cells." (PMID 29596435, 2018).
colon cancer (2 papers, 2023 to 2024). "In addition, FAM110B also acts as an important hub gene in the immune microenvironment of colon cancer cells, and its expression level is negatively correlated with tumor purity and positively correlated with the infiltration of CD4 T cells, macrophages, neutrophils and dendritic cells." (PMID 39170745, 2024).
colorectal cancer (2 papers, 2023 to 2024). A primary or metastatic malignant neoplasm that affects the colon or rectum. "A recent study demonstrated that FAM110B was an immune-related hub gene in colorectal cancer and its expression was positively associated with the infiltration of multiple immune cells, such as CD4 T cells, macrophages, neutrophils, and dendritic cells." (PMID 37310469, 2023). "Further analysis via the HPA database revealed that the expression frequency of FAM110B protein was 100% in tumor types such as thyroid cancer (4/4), colorectal cancer (12/12), head and neck cancer (4/4), renal cancer (12/12), testis cancer (10/10), and endometrial cancer (11/11)." (PMID 39170745, 2024).
glioma (2 papers, 2022 to 2025). A benign or malignant brain and spinal cord tumor that arises from glial cells (astrocytes, oligodendrocytes, ependymal cells). "Additionally, further investigation into the differential roles of these genes across IDH subtypes—such as FAM110B in IDH-mutant gliomas—and their therapeutic potential is needed." (PMID 40018519, 2025).
pancreatic adenocarcinoma (2 papers, 2018 to 2024). "Herein, we found that the expression of FAM110B was decreased along with the tumor differentiation grades, which showed that FAM110B was negatively associated with tumor differentiation and could be served as diagnosis and survival marker of pancreatic adenocarcinoma." (PMID 29596435, 2018). "Finally, 8 differentially expressed genes (ERLIN1, HMGA2, FAM110B, EGFR, MCM2, BCL2L1, E2F1 and RAC1) were considered to be significantly negatively associated with survival (P < 0.05) time of pancreatic adenocarcinoma patients." (PMID 29596435, 2018). "Among these genes, JUB, ERLIN1, FAM110B, MCM2 and BCL2L1 also had a diagnosis value for pancreatic adenocarcinoma." (PMID 29596435, 2018).
Alzheimer disease (1 paper, 2025). A progressive, neurodegenerative disease characterized by loss of function and death of nerve cells in several areas of the brain leading to loss of cognitive function such as memory and language. "Together, they mitigate CDK5-induced neurodegeneration by regulating Tau hyperphosphorylation, oxidative stress, and neuronal apoptosis, making FAM110B and YWHAE potential therapeutic targets in Alzheimer’s disease." (PMID 40018519, 2025).
invasive ductal carcinoma (1 paper, 2020). "The feature plots and spatial feature plots were utilized to illustrate the distribution and expression of CIRBP, FAM110B, ACAA1, ACAT1, and DHCR7, showing that these key genes were highly expressed in the invasive ductal carcinoma tissue (cluster 2, 5, 8)." (PMID 32984314, 2020).
pancreatic cancer (1 paper, 2024). "However, our previous study used WGCNA analysis, combined with a survival analysis curve and the GEPIA database for validation, and discovered that FAM110B was linked to a good survival time for patients with pancreatic cancer, which was consistent with the results of Xi and Zhang (2018)." (PMID 39170745, 2024). "Only FAM110B was found to be a potential immune-related marker for pancreatic cancer in our earlier research." (PMID 39170745, 2024).
tumor (8 papers, 2018 to 2025). "Our models demonstrated that EFHD1 and SLC25A18 were significantly associated with the cell cycle (R2 = 0.790), while SASH1 and FAM110B showed a notable association with tumor stemness (R2 = 0.522)." (PMID 40018519, 2025). "The purpose of the correlational research was to investigate the associations within immunerelated genes, tumor mutation burden, microsatellite instability, immune-related genes, and immunological checkpoints and FAM110B expression." (PMID 39170745, 2024). "FAM110B has been linked to tumor cell growth in earlier research." (PMID 39170745, 2024). "Notably, EFHD1 and SLC25A18 exhibited strong positive correlations with cellular processes related to the cell cycle (Cor = 0.368/0.385, P < =0.001), whereas SASH1 and FAM110B were found to be closely associated with tumor stemness (Cor =0.328/0.427, P < =0.001)." (PMID 40018519, 2025). "Furthermore, FAM110B has been implicated in the regulation of tumor cell surface antigen presentation, which may impact immune evasion by tumor cells." (PMID 37275958, 2023). "Future work is needed to further explore the specific molecular mechanisms of FAM110B in cell cycle regulation, tumor microenvironment (TME) regulation, and immune escape through in vitro experiments and in vivo models." (PMID 39170745, 2024). "Further analysis was done on FAM110B’s function in the tumor immunological milieu, and the connection between FAM110B, immunotherapy response, and associated sensitive medications was assessed." (PMID 39170745, 2024). "Uncertainty exists regarding FAM110B’s function within the tumor microenvironment is unclear as well as pan-cancer." (PMID 39170745, 2024). "We performed an additional investigation to look into the variations in FAM110B expression between tumor and healthy tissue in pan-cancer." (PMID 39170745, 2024). "ESTIMATE, EPIC, QUANTISEQ, and MCPCOUNTER methods were used to calculate the interaction among FAM110B expression as well as the tumor immune microenvironment." (PMID 39170745, 2024). "It appears that FAM110B interacted with immune and tumor cells in tumors because we observed that FAM110B had a positive correlation with a stromal and immune score within 13 malignancies and a negative correlation with a score in 5 cancers." (PMID 39170745, 2024). "We also evaluated the diagnostic potential of FAM13C, FAM110B, and FAM72A in distinguishing UCEC tissues from non-tumor tissues using ROC curves." (PMID 37275958, 2023). "FAM110B has been indicated as a tumor differentiation-related gene that decreases along with the tumor differentiation grades in pancreatic adenocarcinoma." (PMID 35154458, 2022). "In this study, the expression of FAM110B was positively correlated with various immune checkpoints such as PDCD1, CTLA4, EDNRB, TLR4, etc., indicating that FAM110B may be a new target for tumor immunotherapy." (PMID 39170745, 2024). "And the expression trend of FAM110B was decreased along with the tumor differentiation grades." (PMID 29596435, 2018). "However, the expression level of FAM110B was decreased gradually along with the tumor differentiation grades." (PMID 29596435, 2018). "Based on the sequencing data, four tumor differentiation related genes (JUB, HMGA2, FAM110B and MCM2) were selected to perform the expression validation by GEO database." (PMID 29596435, 2018). "Although the role of FAM family genes, such as FAM13C, FAM110B, and FAM72A, in UCEC remains unclear, their relevance to prognosis and the tumor immune microenvironment in UCEC patients warrants further investigation." (PMID 37275958, 2023). "However, the relationship between FAM110B and pan-cancer TME and tumor immune cell infiltration remains largely unknown." (PMID 39170745, 2024). "FAM110B played a negative role in the translational regulation of BRCA1, which is a tumor suppressor of BRCA." (PMID 32984314, 2020).
cancer (5 papers, 2020 to 2024). A tumor composed of atypical neoplastic, often pleomorphic cells that invade other tissues. "We discovered that FAM110B expression often showed a favorable correlation with pan-cancer gene expression associated with m1A, m5C, and m6A, particularly in YTHDF3, YTHDC1, NSUN3, TET2, and METTL14." (PMID 39170745, 2024). "Additionally, single-cell sequencing data showed that FAM110B expression was linked to the cell cycle, distinction, angiogenesis, damaged DNA, hypoxia, inflammation, and stemness in the majority of cancers, according to single-cell sequencing information." (PMID 39170745, 2024). "The findings showed that the expression of FAM110B considerably influenced the degree of immune cell infiltration across most cancer kinds; the immune cell types most closely associated with FAM110B expression were endothelial cells, neutrophils, monocytes/macrophages, and CAFs." (PMID 39170745, 2024). "Ectopic expression of FAM110B can affect the cell cycle progression of G1 phase, which is also one of the characteristics of cancer cells." (PMID 39170745, 2024). "We also looked into the connection between FAM110B mRNA and anti-cancer drug sensitivity using the GDSC database, which will help with patient prediction and clinical therapy selection." (PMID 39170745, 2024). "In a pan-cancer study, we looked at and contrasted the relationship within FAM110B expression, TMB and MSI." (PMID 39170745, 2024). "The FAM110B expression profile, genetic alteration, DNA methylation, RNA modification, clinical importance, and prognostic value in pan-cancer were all systematically analyzed in this work." (PMID 39170745, 2024). "Seven malignancies showed an important distinction when FAM110B expression levels were further evaluated from a pan-cancer perspective at various clinical as well as pathological phases." (PMID 39170745, 2024). "The findings demonstrate that FAM110B influences the development of many cancers via several mechanisms." (PMID 39170745, 2024). "In order to elucidate the expression, aberrant variation, and clinical importance of FAM110B in pan-cancer, a thorough bioinformatics evaluation of the protein was carried out in the present investigation using several databases." (PMID 39170745, 2024). "According to our results, most cancer tissues express abnormal expression of FAM110B mRNA compared to normal tissues." (PMID 39170745, 2024). "FAM110B was discovered to have a substantial positive correlation with the majority of immune-related genes from a pan-cancer standpoint; however, in KIPAN, GBMLGG, and LGG, FAM110B had a negative correlation with the majority of immune-related genes." (PMID 39170745, 2024). "Kaplan-Meier method and COX regression analysis indicated that FAM110B may be a potential prognostic biomarker for a variety of cancers." (PMID 39170745, 2024). "The function of FAM110B in malignant tumors was debatable in the earlier research." (PMID 39170745, 2024). "This study elucidated the role of FAM110B in the occurrence of various tumors from multiple perspectives, and provided a certain basis for further research on the specific mechanism of FAM110B in cancer progression and treatment." (PMID 39170745, 2024). "Thus, a comprehensive analysis of the pan-cancer function of FAM110B is necessary." (PMID 39170745, 2024). "However, the published literature on FAM110B is extremely limited, especially on cancer." (PMID 39170745, 2024). "To assess the connection between FAM110B expression as well as patient survival, we investigated the connection between FAM110B expression and OS, DSS, PFI, and along with DFI within 33 cancer types." (PMID 39170745, 2024). "Based on these findings, the potential mechanism of FAM110B regulation of TME is expected to be revealed from more perspectives in the future, and it is also conducive to providing a theoretical basis for personalized treatment of cancer immunotherapy." (PMID 39170745, 2024).
cancer (continued). "Next, we examined the connection between FAM110B expression and TME in pan-cancer." (PMID 39170745, 2024). "Some genes, which appeared to be virtually switched off in B4GALNT2-expressing cells, are involved in the basic properties of cancer cells, such as stemness (SOX2, ROR1), epithelial to mesenchymal transition (EMT) (NID1, ALX1), and growth (FAM110B, PEG10, MID2)." (PMID 32290493, 2020).
mitochondrial disease (1 paper, 2025). "The identification of mitochondrial disease-specific markers (EFHD1, SASH1, FAM110B, and SLC25A18) highlights shared mechanisms, such as oxidative phosphorylation, calcium signaling, and immune responses, that can serve as therapeutic targets in both AD and GBM." (PMID 40018519, 2025).
FAM110B also shares sentences with these, for which no sentence is quoted: endometrial cancer (2 papers); non-small cell lung carcinoma (2); entropion (1); fibrosarcoma (1); head and neck cancer (1); renal carcinoma (1); stomach adenocarcinoma (1); testis cancer (1); thyroid cancer (1); uterine corpus endometrial carcinoma (1).